HGF (hepatocyte growth factor)
Diseases named in the same sentence as HGF in open-access papers (continued):
Sharing a sentence is not in itself a finding about the gene and the disease.
cancer (continued). "HGF/Met signaling promotes biological activities, resulting in tumor growth, angiogenesis and the development of invasive phenotypes, making this receptor an attractive target for the potential anti-cancer treatment of NSCLC." (PMID 24922520, 2014). "Plasma HGF is another source, which can fluctuate considerably in cancer." (PMID 25534569, 2014). "Furthermore, of the very few investigations of the HGF/Met receptor axis in anoikis control and cancer, a single study has reported a key role for the Met receptor in CRC cells." (PMID 24708867, 2014). "Meanwhile, its cognate ligand HGF has been characterized as a pleiotropic multifunctional factor, involved both in development and tissue repair, as well as pathological processes such as cancer and metastasis." (PMID 28548074, 2014). "In this connection, it is noteworthy that we have previously reported that overexpression of CADM1 in MDCK cells suppresses hepatocyte growth factor (HGF)-induced epithelial-mesenchymal transition (EMT), which is a well-known phenomenon associated with cancer cell invasion and metastasis." (PMID 24503895, 2014). "Therefore, targeting c-Met activity with small molecule inhibitors of the HGF/c-Met axis can be considered a promising approach for cancer treatment and prevention." (PMID 24849787, 2014). "However, in contrast to normal tissue, significantly increased levels of the two-chain activated form of HGF/SF are detectable in various cancer tissues, indicating that the HGF/SF activating machinery is up-regulated in cancer tissues." (PMID 25268161, 2014). "Moreover, our previous study reported that HGF was overexpressed in the EGFR mutant cancer cells that acquired resistance to EGFR-TKIs, indicating endogenous HGF production by cancer cells." (PMID 24952482, 2014). "As the c-Met and EGFR pathways play an essential role in cancer stem cell maintenance, we asked whether the HGF/c-Met and EGF/EGFR pathways influence ACSVL3 expression in GBM stem cell enriched neurospheres." (PMID 24893952, 2014). "Additionally, we observed that treatment of some cancer cell lines with rapamycin and its analogs not only potentiates mitogenic signaling and proliferation induced by HGF, but also stimulates the pro-survival kinase Akt." (PMID 24927123, 2014). "Some studies suggest that HGF may promote the growth and metastasis of some cancer types, probably via the stimulation of cancer cell growth and angiogenesis." (PMID 24604303, 2014). "It has been documented that HGF/c-MET are involved in cancer cell proliferation and invasion." (PMID 24797571, 2014). "Interestingly, genes that have been previously found to be overexpressed in other cancers such as hepatocyte growth factor (HGF), laminin alpha 4 (LAMA4) and androgen receptor (AR) were also found to be more highly expressed in MEi cells compared to BM-MSCs." (PMID 25229469, 2014). "Furthermore, we found in the mid-1990s that stroma-derived HGF is a major contributor to cancer invasion at least in vitro." (PMID 23296269, 2013). "HGF has been reported to promote directional migration and invasion of human cancer cells." (PMID 23320110, 2013). "Other cancer-derived HGF-inducers are IL-1β, b-FGF, PDGF, and TGF-α." (PMID 23296269, 2013). "In addition, few studies have investigated the functional and clinical significance of TGFβ1 and HGF proteins, secreted by dysplasia epithelial cells, cancer cells and stroma fibroblasts, in oesophageal carcinogenesis." (PMID 24137336, 2013). "HGF also protects cancer cells from anoikis or immunological challenge." (PMID 23296269, 2013). "HGF is a stromal-derived factor that stimulates cancer invasion at least in vitro." (PMID 23296269, 2013). "In summary, stroma-derived HGF is required for cancer invasion (i.e., paracrine system)." (PMID 23296269, 2013). "In malignant tumors, HGF is produced by stromal cells, while MET is expressed by cancer cells, which suggested in the mid-1990s that this paracrine loop may determine malignant behaviors." (PMID 23296269, 2013).
cancer (continued). "We cannot exclude that in a context of stimulation by a specific growth factor, decreased IdoA residues may result in a more pronounced migration defect, as seen in cancer cells with HGF." (PMID 23843960, 2013). "This review focuses on the roles of endogenous HGF in cancer biology and pathology." (PMID 23296269, 2013). "The HGF/cMET axis presents a well-established cross-talk with IGF1 and its receptor IGF1R, which are both implicated in the development and progression of a variety of human cancers." (PMID 24005867, 2013). "HGF and its receptor Met are expressed at various levels in various types of cancer cells." (PMID 24386407, 2013). "Recently studies have shown that HGF regulates cell migration and invasion in human cancer cells." (PMID 23320110, 2013). "Purified HGF can stimulate invasive ability in various cancer cells in vitro." (PMID 23977005, 2013). "Recent studies have demonstrated additional roles for the HGF/c-Met signaling cascade in cancer through cross-talk with other signaling cascades, including integrins, class B plexins, proteoglycan CD44, G-protein coupled receptors, and many other receptor tyrosine kinases." (PMID 22962849, 2012). "Targeting HGF/SF-Met pathway is becoming an attractive approach for developing anti-cancer agents." (PMID 23049908, 2012). "TGF-β and HGF induce the EMT in cancer cells and promote invasion and metastasis." (PMID 23109879, 2012). "Our findings suggest that serum HGF may be a predictive marker for cancer death in the general population." (PMID 22672958, 2012). "The pathophysiologic mechanisms for the association between HGF and cancer death in this population were not investigated in this epidemiologic study." (PMID 22672958, 2012). "We investigated whether serum HGF was a predictive marker for cancer death in a population of community-dwelling Japanese." (PMID 22672958, 2012). "However, we found that baseline HGF was similar in the early and late study periods among participants who died of cancer." (PMID 22672958, 2012). "HGF is an angiogenic growth factor which promotes cell migration, proliferation, and invasion, and circulating HGF levels tend to be higher among patients with established cancers." (PMID 22848710, 2012). "For cancer death, mortality increased in relation to HGF (log rank test = 8.23; P = 0.03)." (PMID 22672958, 2012). "Indeed, the activation of HGFR/c-MET has been reported to trigger cancer cell proliferation, migration and invasion and to promote tumor vessel angiogenesis, since HGF directly stimulates endothelial cell proliferation and migration." (PMID 22606042, 2012). "To identify the paracrine factors responsible for T47D carcinoma cell growth stimulation we treated the co-cultures with neutralizing antibodies to eleven factors implicated in stroma-carcinoma interactions (FGF-2, HB-EGF, Heparanase-1, HGF, IGF-1, IGF-2, MT1-MMP, PDGF, SDF-1, TGF-β1, and Wnt-1)." (PMID 23056402, 2012). "Never-the-less, based on these results we suggest that targeting the HGF/c-met/Stat3 pathway could be an especially effective strategy for cancer therapy." (PMID 21595927, 2011). "Importantly, high level of HGF in NAF #200N E4 exhibited significantly higher ability to enhance cancer cell colony formation than NAFs #200N." (PMID 21249190, 2011). "The HGF/c-Met pathway has been implicated in invasion and metastasis in HNSCC and other cancers, both in vitro and in vivo and has been linked to resistance of EGFR inhibitors and cisplatin, making both c-Met and HGF attractive drug targets as well as determinants of treatment." (PMID 24212639, 2011). "HGF secreted by fibroblasts has been shown to mediate proliferation and invasion of cancer cells." (PMID 21249190, 2011). "In addition to its role as a motility and invasion-inducing factor for cancer cells of epithelial origin, HGF has also been shown to contribute to the migration of normal keratinocytes during wound healing." (PMID 20687930, 2010).
cancer (continued). "HGF and its receptor are becoming recognised targets in cancer treatment." (PMID 29147173, 2010). "Together, it further indicates the pivotal role of Rho-C in HGF induced cancer invasiveness." (PMID 29147173, 2010). "A combined strategy in targeting both HGF and RhoC may be an attractive option in cancer therapies, an area that is under active investigation." (PMID 29147173, 2010). "These growth factors can augment the proliferation of residual cancer cells, fibroblasts, and endothelial cells, and some, such as HGF, facilitate the anchorage independent survival of circulating cancer cells and are chemotactic for bone marrow derived progenitor cells." (PMID 19383172, 2009). "In in vitro assays, ENMD-1198 substantially abrogated EGF- and HGF-mediated cancer cell migration and invasiveness, suggesting that this substance could be valuable for reducing HCC metastasis." (PMID 18651980, 2008). "Through Met receptor binding, HGF aberrantly activates the motility/chemoinvasion, proliferation/survival and apoptosis that characterize the epithelial-mesenchymal transition of aggressive carcinomas." (PMID 18941460, 2008). "Increased HGF/c-Met stimulation may therefore play a role in altering cell adhesion in human cancers overexpressing c-Met." (PMID 17242702, 2007). "Thus, the HGF complex in cancer mimics, in some aspect, the classical cytokine–receptor complex abnormalities in cancer: aberrant levels of cytokine coupled with overexpressed HGF receptor and auto-activated receptor signalling pathways." (PMID 17576468, 2007). "HGF regulates cell behaviors in organ development, tissue regeneration and cancer." (PMID 16869958, 2006). "Aberrant HGF/c-Met signalling has been well documented in a variety of human cancers, and our results strengthen the view that also the gastrin signalling pathway could be involved in oncogenesis." (PMID 15846300, 2005). "The mutual interactions between carcinoma cells and hepatocytes mediated by carcinoma-derived HGF may play a role in liver regeneration after partial hepatectomy." (PMID 14960204, 2004). "Moreover, HGF can bind to integrin ligands like FN, enhancing c-Met-integrin cooperation and promoting cell migration, proliferation, and survival, particularly during cancer progression." (PMID 41511363, 2026). "Likewise, IL15 and HGF are known regulators of the inflammatory response in cancer." (PMID 41056512, 2025). "Cancer-associated fibroblasts (CAFs) express and secrete signalling proteins which stimulate cancer cell proliferation, including insulin-like growth factor-1 (IGF-1), hepatocyte growth factor (HGF), stromal-cell-derived factor-1 (CXCL12), and a range of fibroblast growth factors (FGFs)." (PMID 39859271, 2025). "Interestingly, while exerting cytotoxic effects on cancer cells, TAS-115 was associated with an increase in HGF expression, which may indicate a relative survival advantage of NHLFs." (PMID 41289612, 2025). "In various cancers, abnormal activation of the HGF/MET signaling pathway is caused by multiple mechanisms, including gene amplification, overexpression, the presence of different functional gain-of-function mutations, and abnormal secretion of HGF through autocrine or paracrine pathways." (PMID 40136462, 2025). "In addition, a study related to liver cirrhosis found that c-Met binds to HGF and also binds to Fas ligand to form a complex that induces apoptosis in CTLs, an effect that may promote cancer progression." (PMID 39201787, 2024). "Therefore, selective pharmacological targeting of the HGF/c-Met pathway or senescent cells may be a useful strategy for cancer prevention in aging individuals." (PMID 35851277, 2022). "Thus, it is complicated to target just the HGF/MET pathway in cancer therapy." (PMID 35986321, 2022). "Thus, HGF–MET signaling has been considered a promising therapeutic target for a subset of cancers." (PMID 35085554, 2022).
cancer (continued). "In addition, cancer pathways included many pathways of growth factors, such as insulin-like growth factor I, fibroblast growth factor, recombinant human epidermal growth factor, platelet-derived growth factor, and human hepatocyte growth factor." (PMID 35313857, 2022). "Cancer-associated fibroblasts (CAFs), one of the main stroma cells, advance the self-renewal feature of CSCs in HCC and thus could induce sorafenib resistance by secretion of hepatocyte growth factor (HGF)." (PMID 36176764, 2022). "Similarly, HGF can enhance the stem cell-like potential of cancer cells." (PMID 36591565, 2022). "Therefore, any strategies interrupting the HGF/c-Met interaction by either inhibiting the secretion of HGF or repressing the cancer cell responses to HGF could inhibit EMT and metastasis." (PMID 33535458, 2021). "Moreover, the production of TGFβ, leukemia inhibitory factor (LIF), growth arrest-specific protein 6 (GAS6), fibroblast growth factor 5 (FGF5), growth differentiation factor 15 (GDF15), and hepatocyte growth factor (HGF) promotes invasive and proliferative behavior in cancer cells." (PMID 34646829, 2021). "The binding of HGF to c-Met’s Sema domain results in receptor homodimerization, autophosphorylation of tyrosine residues in the tyrosine kinase domain, and downstream activation of some signaling pathways, which contribute to the malignant transformation of a wide range of cancers." (PMID 34804015, 2021). "Moreover, GC-MSC could robustly express hepatocyte growth factor (HGF) as ligand of c‐MET to trigger phosphorylation of its downstream signaling cascade in cancer cells, and aberrant HGF/c-MET axis has been well-established to be critical for GC progression." (PMID 34046337, 2021). "Inhibition of the HGF/c-Met pathway could prevent Treg increase in cancer patients." (PMID 34771724, 2021). "Thus, targeting the HGF/c-Met signaling pathway may be a promising approach for malignant tumors, particularly in the patients with PICs." (PMID 32630328, 2020). "Therefore, the pro-HGF- activation system is significant in cancer progression." (PMID 32290402, 2020). "Therefore, the HGF/c-Met signaling pathway has become a significant target for cancer treatment." (PMID 32521825, 2020). "Using HiP-8, cancer tissues with active HGF could be detected by positron emission tomography." (PMID 33121208, 2020). "The activation of the HGF/MET axis is associated with a series of biological responses, such as proliferation, angiogenesis, migration, invasion, metastasis, and survival, thus contributing to the tumorigenesis, development, and progression of different human cancer types." (PMID 32435640, 2020). "Furthermore, HGF is secreted by both cancer and stromal cells." (PMID 32435640, 2020). "Moreover, epithin/PRSS14 can proteolytically activate growth factors/receptors, including protease-activated receptor 2, hepatocyte growth factor, and Tie2, and thus modulate extracellular environments favoring the migration and invasion of cancer or immune cells." (PMID 32493324, 2020). "However, we were able to assess the effects of HGF/c-MET inhibition on cancer cell invasion." (PMID 32203220, 2020). "Thus, treatment of malignant tumors focusing on the HGF/c-Met signaling pathway may be a promising strategy, particularly for the patients with PICs." (PMID 32630328, 2020). "However, DS can also stimulate the migration of cancer cells via promotion of HGF activity." (PMID 30637950, 2019). "Moreover, some studies have revealed that IL-6 and HGF could help cancer cells to acquire the ability of anoikis resistance, suggesting bypass signaling in the EGFR pathway may play a significant role in anoikis resistance." (PMID 31198634, 2019). "Due to a better understanding of the ligand, the receptor, and activators, many HGF and Met inhibitors have been developed (inhibitors for HGF activators, HGF inhibitors, Met antagonists, and mainly Met kinase inhibitors) and some are being tested in clinical trials for cancer therapy." (PMID 30406111, 2018).
cancer (continued). "Thus, the suppression of HGF/c-MET pathway in cancer cells may also contribute to the antitumor effects of deguelin through modulating the angiogenesis activity of human endothelial cells." (PMID 29416603, 2018). "Meanwhile, neutrophils could potentiate cancer cell migration, invasion and dissemination by secreting immunoreactive molecules such as hepatocyte growth factor, oncostatin M, b2-integrins or neutrophil elastase, which might be another mechanism for CXCL5 promoting cancer progression." (PMID 29743818, 2018). "Therefore, it is worth considering HGF therapy for NAFLD, but the careful selection of patients or animals may have to be considered due to the capacity of HGF to promote cancer progression." (PMID 30083132, 2018). "Thus, inhibition of HGF synthesis or activity in stromal cells may be an effective approach for future targeted cancer therapy." (PMID 30214428, 2018). "Interestingly, HGF may regulate the development of cancer stem cells in HCC via c-Met/FRA1/HEY1 cascade." (PMID 28587113, 2017). "Different cancers may utilize distinct pathways triggered by HGF for migration and metastasis." (PMID 28475121, 2017). "Thus, inhibition of c-Met/HGF pathway may provide an effective therapeutic strategy for cancers with c-Met overexpression." (PMID 29088883, 2017). "Therefore, inhibition of c-Met/HGF signaling may provide an effective therapeutic strategy for cancers showing high c-Met expression." (PMID 29348891, 2017). "HGF produced by both myoepithelial and stromal cells may therefore contribute to the control of the luminal progenitor activity, favoring either their normal expansion during development or aberrant amplification in cancers." (PMID 26165517, 2015). "The question remains whether, in addition to C5a and HGF, other factors that are released in tissues in response to anti-cancer treatment such as certain chemokines or bioactive lipids also increase the release of nucleotides from target cells, but this requires further studies." (PMID 26597723, 2015). "Finally, and in accordance with previous suggestions in different cancer types, we propose that the HGF/MET pathway might act as a primary resistance mechanism for EGFR inhibitors." (PMID 26319934, 2015). "Thus, inhibition of Abl kinases might be exploited for the treatment of cancers driven by hyperactivation of HGF/Met signaling." (PMID 25946048, 2015). "Therefore, we screened a small panel of human cancer cell lines to determine whether rapamycin might potentiate HGF-mediated mitogenesis of some human tumors." (PMID 24927123, 2014). "Indeed, the expression and activity of many growth factors involved in cancer progression are highly dependent on these interactions, with regulation of hepatocyte growth factor (HGF) activity being a typical example of the mutual interaction between cancer cells and stromal cells." (PMID 25268161, 2014). "HAIs may have an important role in cancer cell biology by regulating HGF/SF-activating proteases." (PMID 25268161, 2014). "Additionally, NK2, though its ability to antagonize HGF proliferation could be useful for anti-cancer therapy, however its partial activation of MET may also preclude this application." (PMID 28548073, 2014). "Thus, HGF-induced inhibition of EGFR TKIs is shown to be a common occurrence in human cancers." (PMID 23407898, 2013). "Furthermore, HGF enhances the ability of SDF1 to promote cancer invasion." (PMID 23296269, 2013). "However, kinase inhibitors may have a broader range of application since Met kinase inhibitors may be efficacious in cancers driven by both HGF and c-Met." (PMID 22639908, 2012). "Additionally, the CYP19A1 gene may be relevant to cancer progression, given its potential role in regulating HGF which has angiogenic and mitogenic properties." (PMID 22848710, 2012).